Y_RNA (Y RNA )
Gene: Miscellaneous RNA gene on chromosome 3 (171,439,526 to 171,439,627, forward strand). Ensembl gene ENSG00000222506.
Homologues: Orthologues: chimpanzee Y_RNA (99% identical), mouse Gm55795 (48% identical). Paralogues in human: Y_RNA (65% identical), RNY3P9 (64% identical), Y_RNA (64% identical), Y_RNA (63% identical), Y_RNA (62% identical), Y_RNA (61% identical), RNY3 (60% identical), RNY3P10 (60% identical), RNY3P14 (60% identical), RNY3P16 (60% identical), Y_RNA (60% identical), RNY3P1 (59% identical), and 80 more.